BRAF (B-Raf proto-oncogene, serine/threonine kinase)
Diseases named in the same sentence as BRAF in open-access papers (continued):
Sharing a sentence is not in itself a finding about the gene and the disease.
glioma (continued). "In pediatric low-grade gliomas, patients with BRAF fusion and neurofibromatosis type 1 have favorable outcomes compared to those with BRAF V600E mutation, particularly in association with cyclin-dependent kinase inhibitor 2A (CDNK2A) deletion." (PMID 35884462, 2022). "Nonetheless, advances in molecular biology allowed to identify several druggable alterations in a subset of IDH wild-type gliomas, such as NTRK and FGFR-TACC fusions, and BRAF hotspot mutations." (PMID 35267432, 2022). "It is also interesting that in our molecular Group 4, BRAF V600E was able to impart a better prognosis among the IDH wild-type gliomas." (PMID 35558510, 2022). "Another crucial point regards the appropriate timing for BRAF-targeted therapy initiation in gliomas, which is still unclear." (PMID 36686797, 2022). "The frequency of each genomic aberration of our study was not significantly different from previously reported representative results of The Cancer Genome Atlas glioma cohort, except for the relatively higher frequency of genetic aberrations in BRAF and FGFRs." (PMID 35626060, 2022). "In the recent Rare Oncology Agnostic Research basket trial, the rate of responses to the combination of BRAF/MEK inhibition obtained in high-grade as well as in low-grade glioma cohorts has been encouraging, thus advocating BRAF testing in clinical practice." (PMID 35875139, 2022). "Within the postoperative cohort, BRAF V600E-mutated glioma showed a mean TGV of 0.123 cm3/month (n = 12), while BRAF wild-type glioma showed a significantly lower mean TGV of 0.016 cm3/month (n = 43, p = 0.047)." (PMID 36319795, 2022). "A recently published molecular analysis of more than 200 BRAF-mutant adult gliomas described distinct molecular features compared to pediatric populations, including a lower prevalence of BRAF V600E mutations in adults." (PMID 36619621, 2022). "V600E, is the most frequent BRAF alteration in gliomas, especially in pediatric low-grade astrocytomas, pleomorphic xanthoastrocytoma, papillary craniopharyngioma, epithelioid glioblastoma and ganglioglioma." (PMID 36686797, 2022). "This is consistent with the few papers concerning the potentially better prognosis of BRAF V600E in adult gliomas." (PMID 35558510, 2022). "In children, BRAF alterations are mainly observed in low-grade gliomas including pilocytic astrocytoma and glial-neuronal tumors." (PMID 36686797, 2022). "Our data are supporting and extending recent reports on the use of ddPCR assays to detect mutations in glioma tissue samples, including IDH mutations, TERT promoter mutations, H3-3A mutations, and BRAF duplication." (PMID 35361262, 2022). "Several cases of impressive response to BRAF inhibitors vemurafenib and dabrafenib in high grade gliomas have been reported, including cases of complete radiological disease and prolonged disease control." (PMID 36686797, 2022). "Genetic changes in the BRAF gene are frequently found in pilocytic astrocytomas, a low-grade glioma common in the pediatric population." (PMID 36147920, 2022). "The possibility of introducing targeted therapies into the treatment algorithm represents a paradigm shift for patients with BRAF V600E mutant recurrent high-grade and low-grade glioma and BRAF routine testing should be considered in clinical practice." (PMID 36686797, 2022). "The integration of BRAF inhibitors (BRAFi) in the treatment of patients with gliomas brought a paradigm shift to clinical care." (PMID 36698391, 2022). "A recent phase II trial for high- and low-grade gliomas has illustrated a clinical response with combination dabrafenib, a BRAF inhibitor, and trametinib, a MEK inhibitor." (PMID 35480100, 2022).
glioma (continued). "These four gene-cancer pairs were EWSR1 (26.3% vs. 13.0%) and FLI1 in bone cancer (23.2% vs. 9.6%), BRAF in glioma (3.6% vs. 0.4%), and TEF3 in renal cell carcinoma (8.5% vs. 1.7%)." (PMID 36433963, 2022). "The investigated ddPCR-based assays enable the detection of diagnostically relevant glioma-associated mutations in the IDH1, IDH2, H3-3A, BRAF, and PRKCA genes, as well as in the TERT promoter." (PMID 35361262, 2022). "There is one report of high grade brainstem glioma harboring both PTPN11 and H3F3A mutations, as well as one patient in a cohort of pediatric glioma with co-occurrence of H3 K27M mutations and other alterations in the MAPK pathway, including in BRAF and FGFR1." (PMID 35484611, 2022). "The focus of this review is to summarize the molecular landscape of BRAF across glioma subtypes and the novel therapeutic strategies for BRAF V600E mutated tumors." (PMID 36686797, 2022). "In this review, we outline current achievements and limitations of BRAF inhibition in gliomas, with a special focus on potential mechanisms of resistance." (PMID 36698391, 2022). "Although BRAF changes can occasionally be found in higher grade gliomas, they mostly occur in pilocytic astrocytomas." (PMID 36147920, 2022). "The overall number in this IDH wild type, BRAF mutant group is small (27/1,028 cases), consistent with the overall low percentage of BRAF V600E in adult gliomas." (PMID 35558510, 2022). "CDKN2A genetic alterations are found in low grade gliomas often with BRAF genetic alterations and correlate with later clinical progression." (PMID 35574540, 2022). "We stratified the adult gliomas into 6 molecular grades based on IDH mutations, 1p19q codeletion, TERTp mutation, BRAF mutation, EGFR amplification, 10q loss, and H3 mutations." (PMID 35558510, 2022). "In the preoperative cohort, BRAF V600E-mutated LGG showed a mean TGV of 0.305 cm3/month (n = 8), while BRAF wild-type glioma showed a mean TGV of 0.082 cm3/month (n = 10), while missing statistical significance (p = 0.09)." (PMID 36319795, 2022). "Nonetheless, target therapy with B-RAF and MEK inhibitor agents has shown good results in the treatment of a number of human cancers and glial tumors harboring the V600E BRAF mutation." (PMID 35757402, 2022). "For example, while BRAF fusions are common in low-grade glioma, first-line cytotoxic treatment with carboplatin-vincristine achieves long term survival in ~90% of children." (PMID 35449451, 2022). "Recent intensive genomic and molecular biological analyses of gliomas have identified several significant driver gene mutations in IDH, BRAF, or H3F3." (PMID 34525976, 2021). "This proof of principle study demonstrates the potential of this assay to serve as an adjunctive tool for the detection, monitoring, and molecular characterization of BRAF mutant gliomas and brain metastasis." (PMID 33799709, 2021). "To date, targeted therapy and precision medicine are promising avenues for paediatric gliomas with BRAF V600E and diffuse intrinsic pontine glioma with the H3K27M mutations." (PMID 33557011, 2021). "A body of evidence demonstrates that B-Raf Proto-Oncogene or V-Raf Murine Sarcoma Viral Oncogene Homolog B (BRAF) and histone H3 mutations are valuable biomarkers for paediatric low-grade gliomas (pLGGs) and high-grade gliomas (pHGGs)." (PMID 33557011, 2021). "There are many well-studied pathogenic genes and regulators of gliomas, including IDH1/2, 1p/19q codeletion, integrin β1 (ITGB1) and v-raf murine sarcoma viral oncogene homolog B1 (BRAF) V600E mutation." (PMID 34722629, 2021).
glioma (continued). "Pre-clinical data have suggested synergy between MEK1/2 and BRAF inhibitors with radiotherapy for pediatric gliomas, but concerns regarding toxicity of concurrent treatment exist." (PMID 34604027, 2021). "In particular, gain of function of BRAF plays a critical role in a heterogeneous group of gliomas, as well as in the majority of metastatic melanoma and other cancers (including papillary thyroid cancer, colon carcinomas, hairy cell leukaemia)." (PMID 34360713, 2021). "In CNS tumors, including gliomas, clinical experience with a combination of BRAF and MEK inhibitors has also been reported." (PMID 33673070, 2021). "Of these, BRAF harbored a level 1 alteration for several non-CNS cancers, indicating its status as FDA-recognized predictive biomarker of response to an FDA-approved drug; notably, this FDA indication does not include gliosarcoma." (PMID 34504233, 2021). "Encouraged by these results, we reviewed glioma cases at Moffitt Cancer Center (MCC), who had similar molecular profiling, and found 3% patients with gliomas carrying BRAF mutations." (PMID 31748891, 2020). "As well as an enhanced response to BRAF inhibition when combined with autophagy inhibition in glioma cell lines." (PMID 31748891, 2020). "The crossover Kaplan–Meier survival curves and log rank (Mantel–Cox) test were performed to explore the influence of BRAF gene alteration on the overall survival of glioma patients." (PMID 33489866, 2020). "Apart from ependymoma, homozygous deletions of CDKN2A have recently been described as adverse prognostic marker for other CNS tumors, including anaplastic IDH-mutant gliomas and BRAF-mutant low-grade gliomas." (PMID 32514758, 2020). "The topic-by-topic inspection reveals that the most improvement in P@10 is observed for topic 44 (glioma, BRAF)." (PMID 33349237, 2020). "Adult patients with glioma with BRAFAMP and IDH1/2WT had worse prognoses compared with those with BRAF mutation and BRAFAMP and IDH1/2MT." (PMID 33489866, 2020). "We then analyzed the expression of GPR133 across glioma molecular subtypes, as defined by the IDH1/2 mutations, 1p19q codeletion, and BRAF status." (PMID 32642706, 2020). "In the present study, we summarized the clinical and basic molecular pathological characteristics of 83 patients with spinal cord astrocytomas, thus revealing the prognostic value of the BRAF V600E and TERT promoter mutations in grade II and III gliomas." (PMID 32228694, 2020). "For example, the recurrent fusion KIAA1549-BRAF is found across 66–80% of low grade gliomas and results in a fusion transcript that has constitutive BRAF kinase activity." (PMID 33317447, 2020). "A phase II trial (NCT02684058) is currently underway studying dabrafenib and trametinib in children and adolescent patients with BRAF V600E low grade glioma and adults with relapsed or refractory high grade glioma." (PMID 33042847, 2020). "The BRAF V600E mutation, among other molecular aberrations of this gene (in particular the presence of KIAA1549-BRAF fusions), is found in several CNS tumors, including gliomas and glioneuronal tumors." (PMID 32879641, 2020). "Detection of a BRAF V600E mutation next to mutations in NF1 and JAK3 as well as deletions of KIT and PDGFRA led to the diagnosis of a pediatric-type low-grade glioma or ganglioglioma." (PMID 32758285, 2020). "For example, all four IDH1-wt glioblastoma GSCs with BRAF hotspot mutations (V600E and D594H) were classified into the E&F-independent group, although BRAF alterations are rarely observed in adult HGG or other diffusely infiltrating gliomas (2–5%)." (PMID 32120790, 2020). "As all the patients enrolled in this study were adults, our findings provide insight into the effects of BRAF alterations in adult glioma." (PMID 33489866, 2020).
glioma (continued). "Strikingly, BRAF-inhibition also blocked activating phosphorylation of ETS1 selectively in BRAFV600E-mutant glioma cells." (PMID 31391125, 2019). "In 2016 the WHO classification of CNS tumors included another BRAF-associated glial tumor, the diffuse leptomeningeal glioneuronal tumor (DLGT), as a molecularly defined entity of BRAF-associated neoplasm." (PMID 31181803, 2019). "Accordingly, ETS-factor inhibition is a promising therapeutic option for therapy-resistant BRAF-mutant glioma." (PMID 31391125, 2019). "Pathologic activation of the MAPK signaling pathway in cancer cells is well-known to cause oncogene induced senescence (OIS), a tumor suppressing mechanism which has also been described in BRAF-altered glioma." (PMID 31391125, 2019). "The most common fusion is KIAA1549–BRAF, which was first identified in low-grade glioma and is composed of the N-terminal dimerization domain of KIAA and the C-terminal kinase domain of BRAF." (PMID 31466300, 2019). "In this context, OIS and replicative senescence have been described as central obstacles for proliferation in BRAF-altered glioma cells." (PMID 31391125, 2019). "Currently several clinical trials are investigating targeted treatment in recurrent BRAF V600E-mutant gliomas of children and young adults (NCT01748149 and NCT02684058) as well as pediatric primary low-grade gliomas (NCT02684058)." (PMID 31181803, 2019). "Rather, it harbors a BRAF V600E mutation and focal CDKN2A/B deletion, classifying this model as a high-grade glioma, herein denoted as an astrocytoma." (PMID 31693904, 2019). "Summarizing, we prove that telomerase re-activation based on a mutant TERT promoter sequence in BRAFV600E-mutant glioma is driven by oncogenic BRAF signaling predominantly via downstream activation of ETS-factors." (PMID 31391125, 2019). "Pilocytic astrocytoma (PA), the most common childhood brain tumor, is a low-grade glioma with a single driver BRAF rearrangement." (PMID 31427603, 2019). "OS in this case was 28.8 months, suggesting a benefit of targeted treatment in BRAF commutated H3K27M glioma." (PMID 31998633, 2019). "The discovery of genomic aberrations in BRAF as drivers of certain glioma subtypes has resulted in a magnificent extension of the therapeutic repertoire for these patients." (PMID 31391125, 2019). "We recommend that the neuro-oncologist consider using these drugs primarily in the setting of a clinical trial for patients with BRAF-altered glioma in order to advance our knowledge of their efficacy in this patient population." (PMID 31466300, 2019). "Pilocytic astrocytoma is a low-grade pediatric glioma, characterized by a single BRAF rearrangement." (PMID 31427603, 2019). "In vitro, BRAFV600E/TERT promoter double-mutant glioma cells showed exceptional sensitivity towards BRAF-targeting agents." (PMID 31391125, 2019). "In contrast to low-grade glioma, BRAF V600E in pGBM appears to confer a more indolent clinical course compared to pGBM with wild-type BRAF." (PMID 31466300, 2019). "Even though there is still a lot of room for improvement, these findings are encouraging to hopefully provide improved substances and more efficacious combination therapies to treat central nervous system tumors with BRAF alterations in the future." (PMID 31181803, 2019). "In order to further understand the interplay between BRAF V600E mutation and the chromosomal region abrogating the CDKN2A gene: 9p21, a cohort of 100 pediatric gliomas was retrospectively analyzed." (PMID 30558563, 2018). "Pleomorphic xanthoastrocytoma is a circumscribed glial neoplasm that is genetically characterized by concurrent CDKN2A homozygous deletion and BRAF p.V600E mutation (or less commonly BRAF or RAF1 fusion)." (PMID 29880043, 2018). "In other low grade gliomas such as pleomorphic xanthoastrocytoma (PXA) and pilocytic astrocytomas (PA) the BRAF V600E mutation has also been observed." (PMID 29963264, 2018).
glioma (continued). "Recently, molecular biomarkers including the 1p/19q co-deletion, BRAF mutation, IDH1/2 mutation, and TERT mutation have been widely used in the diagnosis, treatment, and prognostic prediction of gliomas." (PMID 28978019, 2017). "In our present study, we describe sensitivity to targeted inhibitors and resistance/escape mechanisms driven by BRAF-fusions that are prevalent in pediatric low-grade gliomas and found in several adult cancers." (PMID 29156677, 2017). "In secondary high glade gliomas, BRAF V600E and CDKN2A deletion were as high as 39% and 57%, respectively." (PMID 29152094, 2017). "Recently, molecular biomarkers including 1p/19q co-deletion, BRAF mutation, IDH1/2 mutation, and TERT mutation have been widely used for glioma diagnosis, treatment, and prognosis prediction." (PMID 28978019, 2017). "In contrast to IDH1-mutant gliomas, ATRX mutations associated with H3G34V, ZMYND11, EP300, or BRAF V600E were stable across the disease course in our study." (PMID 29084603, 2017). "Since BRAF V600E mutant gliomas often develop acquired resistance to FDA approved small molecule inhibitor, our PDOX model would be a powerful tool to conduct pre-clinical testing of new BRAF V600E targeting inhibitors." (PMID 29152094, 2017). "Fusion genes or mutations involving BRAF, FGFR1 and the MAPK pathway have been described in other glioneuronal or glial tumors such as ganglioglioma or pilocytic astrocytoma." (PMID 26671581, 2015). "Histological subgroups of low-grade and high-grade gliomas demonstrating in which tumors the BRAF gene fusion has been identified." (PMID 25785246, 2015). "In the current study, we used the well-established RCAS/TVA glioma mouse model to assess the role of the BRAF-KD in glioma development in vivo." (PMID 25821557, 2015). "Targeted monotherapy against BRAFV600E displays efficacy in pre-clinical models of glioma, however xenograft tumors adapt rapidly and escape from the growth-inhibitory effects of BRAF-targeted therapy." (PMID 26023796, 2015). "Gene fusions involving members of the MAPK pathway including BRAF and in which low-grade gliomas the fusions have been identified." (PMID 25785246, 2015). "Cerebellar engraftment of NSCs expressing KIAA1549:BRAF in mice led to the formation of glioma-like lesions after a latency of 6 months." (PMID 25821557, 2015). "This suggests that the level of canonical BRAF signaling plays a role in glioma development and progression." (PMID 25821557, 2015). "In conclusion, this case provides evidence that BRAF inhibition has important therapeutic potential in CNS tumors, including the most aggressive high grade gliomas." (PMID 24725538, 2014). "Excitingly, pre-clinical data in intracranial xenografts of pediatric gliomas suggest a role for BRAF V600E inhibitors in the treatment of pediatric gliomas." (PMID 23717811, 2013). "Two-thirds of pilocytic astrocytomas, a low-grade pediatric glioma, contain a translocation within the BRAF gene called KIAA1549:BRAF that causes an overactivation of the MEK/MAPK signaling cascade." (PMID 23717811, 2013). "Given the prevalence of activation of the PI3K/mTOR axis and BRAF V600E mutations in pediatric tumors, we designed a pre-clinical study to determine whether inhibitors of mTOR and of BRAF V600E cooperate to enhance cytotoxicity specifically in pediatric low-grade gliomas." (PMID 23717811, 2013). "This is the first in vivo demonstration of combinatorial activity of an mTOR inhibitor with a BRAF inhibitor in gliomas, and will inform future clinical trials in pediatric brain tumor patients." (PMID 23717811, 2013). "Most critical now will be to demonstrate sensitivity of BRAF V600E-positive glioma cell lines and tumors to BRAF targeted therapeutics." (PMID 21479234, 2011). "Our results showed that BRAF V600E mutation, alone or in combination with CDKN2A homozygous deletion, did not have a significant impact on PFS in pediatric patients with high-grade glioma." (PMID 40860828, 2025).